DHX34 (DExH-box helicase 34)
Description:
Probable ATP-binding RNA helicase required for nonsense-mediated decay (NMD) degradation of mRNA transcripts containing premature stop codons. Promotes the phosphorylation of UPF1 along with its interaction with key NMD pathway proteins UPF2 and EIF4A3. Interaction with the RUVBL1-RUVBL2 complex results in loss of nucleotide binding ability and ATP hydrolysis of the complex. Negatively regulates the nucleotide binding ability and ATP hydrolysis of the RUVBL1-RUVBL2 complex via induction of N-terminus conformation changes of the RUVBL2 subunits.
Synonyms: DDX34; KIAA0134
Tractability: PROTAC: ubiquitination databases record sites on it; its protein half-life has been measured.
Gene: Protein-coding gene on chromosome 19 (47,349,312 to 47,383,247, forward strand). Ensembl gene ENSG00000134815.
Subcellular location (Human Protein Atlas): Nucleoplasm
Gene Ontology:
Molecular function: ATP hydrolysis activity; protein binding; protein-containing complex binding; RNA binding; helicase activity; ATP binding; nucleic acid binding; RNA helicase activity
Biological process: negative regulation of nuclear-transcribed mRNA catabolic process, nonsense-mediated decay; nuclear-transcribed mRNA catabolic process; positive regulation of phosphorylation; nuclear-transcribed mRNA catabolic process, nonsense-mediated decay
Cellular component: membrane
Genetic constraint (gnomAD): Loss-of-function variants: 98 observed, 110.67 expected, observed/expected ratio (o/e) 0.89, 90% interval 0.75 to 1.05. The upper end of that interval is the gene's LOEUF score, 1.05, which puts it in group 4 of 6, group 1 being the genes least tolerant of losing a copy. Missense variants: 1,560 observed, 1,569.6 expected, observed/expected ratio (o/e) 0.99, 90% interval 0.95 to 1.04. Synonymous variants: 688 observed, 664.38 expected, observed/expected ratio (o/e) 1.04, 90% interval 0.97 to 1.1.
Homologues: Orthologues: chimpanzee DHX34 (99% identical), macaque DHX34 (97% identical), dog DHX34 (89% identical), rabbit DHX34 (88% identical), mouse Dhx34 (87% identical), guinea pig DHX34 (85% identical), rat Dhx34 (85% identical), pig DHX34 (78% identical), tropical clawed frog dhx34 (62% identical), zebrafish dhx34 (59% identical), Drosophila melanogaster CG32533 (41% identical), Caenorhabditis elegans smgl-2 (35% identical). Paralogues in human: DHX57 (25% identical), DHX29 (23% identical), DHX15 (23% identical), DHX8 (23% identical), YTHDC2 (22% identical), DHX16 (22% identical), DHX38 (22% identical), DHX36 (22% identical), DHX9 (21% identical), TDRD9 (21% identical), DHX30 (21% identical), DHX37 (21% identical), and 6 more.
Diseases named in the same sentence as DHX34 in open-access papers:
DHX34 is named in the same sentence as 22 diseases in open-access papers, as found by Europe PMC text mining. Sharing a sentence is not in itself a finding about the gene and the disease. The quoted sentences say what the papers report.
acute myeloid leukemia (4 papers, 2020 to 2024). Acute myeloid leukemia (AML) is a group of neoplasms arising from precursor cells committed to the myeloid cell-line differentiation. "Heterozygous mutations in DHX34 were identified in four families affected with inherited acute myeloid leukemia (AML) and myelodysplastic syndrome (MDS)." (PMID 37605642, 2023). "We previously showed that germline DHX34 mutations associated to familial myelodysplasia (MDS)/acute myeloid leukemia (AML) predisposition abrogate its activity in NMD." (PMID 35768279, 2022). "Interestingly, variants of DHX34 unable to facilitate UPF1 phosphorylation have been found as pathogenic versions specific to inherited forms of acute myeloid leukemia (AML) and myelodysplastic syndrome (MDS)." (PMID 33205750, 2020). "For instance, AS of DHX34 accounts for sporadic acute myeloid leukemia (AML) that phenocopies the loss-of-function mutation of DHX34 observed in familial AML cases." (PMID 39550559, 2024). "We previously identified heterozygous mutations in DHX34 in four families affected with inherited acute myeloid leukemia (AML) and myelodysplastic syndrome (MDS) and showed that these mutations abrogated the NMD function of DHX34 using an NMD reporter." (PMID 35768279, 2022). "Only recently, germline pathogenic variants of DHX34 were found in four families as specific to familiar forms of acute myeloid leukemia (AML) and myelodysplastic syndrome (MDS)." (PMID 33205750, 2020). "We previously identified heterozygous germline variants in DHX34 in four families affected of inherited acute myeloid leukemia (AML) and myelodysplastic syndrome (MDS) and showed that all these variants abrogated DHX34 NMD activity." (PMID 35768279, 2022).
neuroblastoma (2 papers, 2020 to 2023). Neuroblastoma (NB) is the most common solid, extracranial childhood tumor. "In 2013, Longman and colleagues found two additional factors involved in the NMD pathway: DExH-Box Helicase 34 (DHX34) and neuroblastoma-amplified sequence (NBAS) proteins; indeed, the depletion of either of the two reduced the expression of core NMD factors." (PMID 36768954, 2023).
adrenocortical cancer (1 paper, 2024). "Furthermore, analysis of the HPA dataset revealed that DHX34 mRNA is mainly expressed in adrenocortical cancer, cervical cancer, and liver cancer cell lines." (PMID 39668816, 2024).
bladder cancer (1 paper, 2024). "Furthermore, our analysis of the mutation frequency of the DHX34 gene across various tumor types showed that cervical cancer (20%), esophagogastric cancer (15.34%), and bladder cancer (13.04%) had the highest alteration frequency, ranking among the top three." (PMID 39668816, 2024).
bone marrow failure (1 paper, 2020). "This includes genes mutated in rare hematological syndromes (ADA, GP6, IL17RA, PRF1, and SEC23B), reported in prior MDS/AML or inherited bone marrow failure (IBMF) series (DNAH9, SH2B3, and NAPRT1), or novel loci where loss-of- function of the identified germline variants was demonstrated (DHX34)." (PMID 32098966, 2020).
breast carcinoma (1 paper, 2020). "Although some genes, such as DHX34 and RELB, have not yet been shown to be directly related to breast cancer, it’s possible that they could lead to the discovery of new breast cancer related genes or biomarkers." (PMID 33371906, 2020).
cervical cancer (1 paper, 2024). A primary or metastatic malignant neoplasm involving the cervix. "Among cervical cancers, DHX34 mutation frequency was the highest." (PMID 39668816, 2024).
colonic carcinoma (1 paper, 2024). "The expression of DHX34 was further validated in our cancer cohorts using qRT-PCR and WB among 4 different types of cancer, including colonic carcinoma, LIHC, LUAD, and STAD." (PMID 39668816, 2024).
low grade glioma (1 paper, 2024). A grade I or grade II glioma arising from the central nervous system. "High expression of DHX34 is associated with poor prognosis in tumors such as adrenocortical carcinoma (ACC), renal papillary cell carcinoma (KIRP), low-grade glioma (LGG), and LIHC." (PMID 39668816, 2024).
myeloid leukemia (1 paper, 2022). A clonal proliferation of myeloid cells and their precursors in the bone marrow, peripheral blood, and spleen. "For this, we performed RNA sequencing (RNA-seq) of the immortalized K562 myeloid leukemia cell line following depletion of DHX34, which was verified by qRT-PCR and changes in gene expression (DGE) and in alternative splicing were assessed." (PMID 35768279, 2022).
cancer (3 papers, 2022 to 2025). A tumor composed of atypical neoplastic, often pleomorphic cells that invade other tissues. "Given that the AUC of the ROC exceeded 0.7 in 17 malignancies and 0.9 in 7 cancers, increased DHX34 expression holds promise as a novel diagnostic marker in clinical practice." (PMID 39668816, 2024). "The correlation analysis, logistic regression analysis, and subgroup analysis revealed a significant association between DHX34 and multiple clinical-pathological factors associated with cancers." (PMID 39668816, 2024). "Our findings revealed that DHX34 exerts a pro-cancerous effect on cancer cells, indicating its potential as a diagnostic and prognostic biomarker in pan-cancer." (PMID 39668816, 2024). "To assess the mutation of DHX34 in pan-cancer, we conducted a comprehensive study using the cBioPortal database and found that DHX34 was altered in 5% (128/2565) of pan-cancer patients." (PMID 39668816, 2024). "Therefore, the objective of our research was to investigate the expression levels of DHX34 and their association with diagnosis and prognosis across various cancer types." (PMID 39668816, 2024). "Additionally, we delved into the prognostic and diagnostic significance of DHX34 in diverse cancer forms." (PMID 39668816, 2024). "Alterations in the DHX34 gene were observed in approximately 5% of pan-cancer patients, with amplification representing the largest proportion of these changes." (PMID 39668816, 2024). "These hub genes exhibited a positive correlation with DHX34 expression, suggesting their comparable involvement in cancer biology." (PMID 39668816, 2024). "The results indicated that most of these genes displayed a positive correlation with DHX34 in pan-cancer." (PMID 39668816, 2024). "While DHX34's impact on pan-cancer was discussed, it is important to acknowledge that we did not look into the molecular mechanism of DHX34 in malignancies in our study." (PMID 39668816, 2024). "Collectively, these findings indicated that DHX34 holds promising potential in predicting immune-related phenotypes in pan-cancer." (PMID 39668816, 2024). "This comprehensive study provides insights into the role of DHX34 as a therapeutic target in pan-cancer." (PMID 39668816, 2024). "The present study focused on elucidating the function of DHX34 in pan-cancer through a bioinformatics approach." (PMID 39668816, 2024). "This analysis identified ten hub genes, and we subsequently explored their relationship with DHX34 expression across various cancer types." (PMID 39668816, 2024). "We analyzed the co-expressed genes of DHX34 in eight cancer types using RNA sequencing data obtained from the TCGA database and visualized the 20 most highly correlated genes." (PMID 39668816, 2024). "Our study revealed significant correlations between DHX34 expression and multiple immune factors in pan-cancer." (PMID 39668816, 2024). "We, therefore, hypothesize that cancer patients with high DHX34 expression would experience improved survival following immunotherapy." (PMID 39668816, 2024). "The Protein-Protein Interaction (PPI) network and GSCALite database suggested that DHX34 and its ten co-expression genes might promote cancer progression by regulating the cell cycle." (PMID 39668816, 2024). "Forest map showing the prognostic value of DHX34 in a variety of cancer types." (PMID 39668816, 2024). "Finally, we explored the relationship between DHX34 expression and the sensitivity of cancers to immune or targeted therapies." (PMID 39668816, 2024). "Furthermore, our research has uncovered an association between DHX34 overexpression and reduced sensitivity of cancer cells to multiple anticancer drugs, which provides a compelling rationale that DHX34 may act as a target for cancer-specific chemotherapeutic agents." (PMID 39668816, 2024).
cancer (continued). "Expression validation in the transcriptome, TCGA–BLCA, and GSE13507 datasets confirmed the up-regulation of APOL1, DHX34, and TNK2, and the down-regulation of AHNAK, CSPG4, NCAM1, and PCDHB4 in the cancer group." (PMID 40908816, 2025). "To investigate the prognostic value of DHX34, we performed univariate Cox regression analysis to evaluate DHX34 expression with OS, DSS, and PFI in pan-cancer." (PMID 39668816, 2024). "Despite these insights, however, there is no comprehensive study on the relationship between DHX34 and pan-cancer." (PMID 39668816, 2024). "Then, we detected the correlation of DHX34 expression with both TMB and MSI in pan-cancer." (PMID 39668816, 2024). "Our calculations revealed that the DHX34 low group exhibited lower TIDE scores in KIRP, LGG, LIHC, and SKCM, indicating that lower DHX34 expression predicts a more favorable ICI treatment response in these cancers." (PMID 39668816, 2024). "Moreover, we examined the interplay between DHX34 expression levels and TIME in pan-cancer." (PMID 39668816, 2024). "DHX34 was overexpressed in those cancer tissues compared to their corresponding non-tumor tissues." (PMID 39668816, 2024).
blood disorders (1 paper, 2022). "As a first attempt to investigate the functional role of DHX34 in blood disorders, we focused on the described role of DHX34 in NMD (Hug and Cáceres 2014) and in pre-mRNA splicing (this study) in a more relevant cellular system." (PMID 35768279, 2022).
infection (1 paper, 2023). The state of being infected such as from the introduction of a foreign agent such as serum, vaccine, antigenic substance or organism. "In a similar timeframe, we found that DHX34 was significantly decreased at 6 h post-infection as compared to that at earlier time points (1 and 3 h post-infection), while at 9 h after infection it was significantly higher compared to that at 1 and 6 h after infection." (PMID 36768954, 2023). "We found a significant decrease of DExH-Box Helicase 34 (DHX34), suppressor with morphogenetic effect on genitalia 5 (SMG5), and SMG7 expression at 6 h post-infection, followed by a significant increase of these genes and also UPF1 and UPF2 at 9 h post-infection." (PMID 36768954, 2023).
tumor (1 paper, 2024). "we, therefore, hypothesize that DHX34 may enhance the function or quantity of tumor-associated macrophages, further exacerbating the growth and aggressiveness of the tumor." (PMID 39668816, 2024). "Crucially, our qRT-PCR, WB, and IHC experiments confirmed that both the mRNA and protein expression of DHX34 are elevated in tumor tissues compared to normal tissues." (PMID 39668816, 2024). "Subsequently, a comparison was made between the mRNA and protein expression levels of DHX34 in tumor tissues versus those in normal tissues." (PMID 39668816, 2024). "Intriguingly, a positive correlation was observed between DHX34 expression and Mutational Burden (TMB) across 12 tumor types, and Microsatellite Instability (MSI) across 10 tumor types." (PMID 39668816, 2024). "Furthermore, we detected the relationships between DHX34 expression and various tumor characteristics, including TMB, MSI, Tumor Immune Microenvironment (TIME), Immune Checkpoint Inhibitors (ICI) response, and drug resistance." (PMID 39668816, 2024). "Our findings suggest that the high expression of DHX34 genes in tumor cells may promote mitosis and expedite the cell cycle, thereby contributing to accelerated tumor growth." (PMID 39668816, 2024). "Our findings collectively suggest that DHX34, through its involvement in cell cycle regulation and gene transcription, may play a pivotal role in tumor development and progression." (PMID 39668816, 2024).
DHX34 also shares sentences with these, for which no sentence is quoted: myelodysplastic syndrome (3 papers); glioma (1); liver cancer (1); malignant mesothelioma (1); myeloid malignancies (1); Pan (1); renal papillary cell carcinoma (1); Skin Cutaneous Melanoma (1).